CD4 (CD4 molecule)
Diseases named in the same sentence as CD4 in open-access papers (continued):
Sharing a sentence is not in itself a finding about the gene and the disease.
tuberculosis (continued). "The risk of tuberculosis was the highest in those with low CD4+ cell counts and in those of Black African ethnicity." (PMID 32501837, 2020). "A lower current CD4 T-cell count, a history of tuberculosis and >500 copies of HIV RNA/mL associated weakly (p < 0.20) with HIV-SN." (PMID 31936167, 2020). "A lower nadir CD4 T-cell count and a history of tuberculosis were weakly linked with HIV-SN (p < 0.20) and were also included multivariate analyses." (PMID 31936167, 2020). "Tuberculosis, the leading cause of death among adults, was associated with increased risk of dying at all CD4 counts (HR 2.11; 95% CI 1.50–2.98)." (PMID 32481319, 2020). "In humans, CD4+ T cells are essential in fighting mycobacterial infections evidenced by a much higher risk of active tuberculosis in HIV coinfection with defective CD4+ T cell responses and conventional CD8+ T cells suppress mycobacterial growth." (PMID 32582206, 2020). "Post-tuberculosis lung disease is common in patients with HIV-associated TB at high risk of TB-IRIS (CD4 count ≤100 cells·μL−1)." (PMID 31862762, 2020). "It suggested that Uyghur ethnicity, female, lower CD4 counts, lower BMI, self-reported tuberculosis (TB) infection and oral candidiasis were the risk factors of anaemia." (PMID 30816082, 2019). "We evaluated the association between tuberculosis disease category and 12-month survival using Cox regression, adjusting for age, sex, and CD4 count." (PMID 30611192, 2019). "Previous publications have reported that IFNγ-producing and bifunctional/polyfunctional CD4+ T cells are associated with protection from tuberculosis in experimental models." (PMID 31120957, 2019). "Early (within 2–4 weeks of commencing anti-tubercular therapy) antiretroviral (ART) therapy of HIV-1-associated tuberculosis is associated with survival benefit in patients with low CD4 counts." (PMID 29492737, 2018). "We show differences between groups in tuberculosis diagnosis, although with a corresponding mortality benefit only for predefined high-risk groups (ie, low CD4 cell counts, low haemoglobin, or clinically suspected tuberculosis)." (PMID 30032978, 2018). "It is now clear that cessation of bacterial growth correlates with the arrival of IFN-γ-producing Th1-polarized CD4+ T-cells in the lungs and that a loss of CD4+ T-cells increases the likelihood of succumbing to tuberculosis." (PMID 29736404, 2018). "Chronic pulmonary inflammation marked predominantly by CD4+IFN-γ+ cells is the hallmark of tuberculosis pathogenesis in immunocompetent adults, who are substantially affected by this disease." (PMID 30584243, 2018). "The hallmark of the protective immune response against tuberculosis is the differentiation of INF-γ-producing CD4+ cells and the activation of inflammatory M1 macrophages." (PMID 30584243, 2018). "Whilst the majority of opportunistic infections develop during advanced HIV-associated immunodeficiency, tuberculosis occurs over a wide range of CD4+ T-cell counts." (PMID 29029171, 2017). "We explored the potential association between the fecal microbiota and CD4+ cells in the two types of tuberculosis." (PMID 29204120, 2017). "Among HIV-positive patients, every 50-cells/mm3 increase in CD4+ cell count at tuberculosis diagnosis was associated with 4% lower odds of empirical treatment." (PMID 28804167, 2017). "None of the IL-7R variants were differentially expressed on the mRNA level of CD4+ T cells between tuberculosis patients and healthy contacts." (PMID 28582466, 2017). "The two groups were comparable in terms of gender composition, risk of a new opportunistic infection (active tuberculosis) or levels of current follow-up CD4 counts." (PMID 29237401, 2017). "Independent associations between several clinical characteristics (Male gender, CD4 count, tuberculosis, and renal failure) and a higher risk of IHM in older adults with HIV infection were noted in our study." (PMID 28533849, 2017).
tuberculosis (continued). "Loss of CD27 expression on M. tuberculosis–specific IFN-γ+ CD4+ T cells has been shown to be associated with tuberculosis when compared to LTBI in multiple studies." (PMID 28329119, 2017). "The reduction of the number of peripheral CD4+ T cells associated with HIV progression correlates with increased tuberculosis susceptibility." (PMID 27462092, 2016). "HIV-1 is recognized to increase the risk for tuberculosis even before CD4+ T cell deficiency is profound." (PMID 27865393, 2016). "CD4+ T cells producing interferon-γ are crucial for protection against Mycobacterium tuberculosis infection and are the cornerstone of tuberculosis vaccination and immunological diagnostic assays." (PMID 26379242, 2015). "We demonstrated that lower CD4 count, hemoglobin ≤8.5 g/dL, and the presence of microbiologically confirmed tuberculosis were associated with increased adjusted odds of M. tuberculosis bacteremia among HIV-infected patients suspected to have tuberculosis." (PMID 25582793, 2015). "Among HIV-infected tuberculosis suspects, mycobacteremia was associated with lower CD4 count, hemoglobin ≤8.5 g/dL, and the presence of microbiologically confirmed tuberculosis." (PMID 25582793, 2015). "Key factors for the increased susceptibility of HIV patients to develop tuberculosis include general as well as Mycobacterium tuberculosis specific CD4 T cell depletion." (PMID 25758583, 2015). "In multivariable analysis, lower CD4 count (OR 0.85 per 10-cell increase, p = 0.012), hemoglobin ≤8.5 g/dL (OR 5.8, p = 0.049), and confirmed tuberculosis (OR 17.4, p = 0.001) were associated with M. tuberculosis bacteremia." (PMID 25582793, 2015). "Risk factors for attrition included young age, low CD4 percentage, underweight, active tuberculosis, and enrollment/treatment initiation after 2006." (PMID 26287397, 2015). "The majority of the patients in this study sought care after they had developed the symptoms associated with a low CD4 cell count, started feeling sick, or had another health complaint, such as tuberculosis (TB) or a Sexually Transmitted Infection (STI)." (PMID 25794189, 2015). "Several previous reports also suggest a deficiency in this activation in active tuberculosis patients, in both CD4+ T cells and CD8+ T cells." (PMID 26000298, 2015). "Each OI diagnosed showed strong association with CD4 count less than 200/mm3; oral candidiasis (OR = 27.20, P < 0.001), tuberculosis (OR = 9.40, P < 0.001), skin fungal infections (OR = 11.10, P = 0.008) and pneumonia (OR = 8.21, P = 0.032)." (PMID 24330921, 2013). "After adjustment for baseline body mass index, CD4 count and hemoglobin, occurrence of tuberculosis-IRIS was independently associated with 48-week mortality (aOR 2.72 95%CI 1.14-6.54)." (PMID 24367678, 2013). "active tuberculosis was associated with an increased frequency of mono- or dual-functional CD4+ and CD8+ M. tuberculosis-specific T cells that secrete IFN-γ and/or TNF-α making these subsets potential biomarkers of disease activity." (PMID 23966657, 2013). "Infections such as pneumonia and tuberculosis (TB) have been associated with decreased CD4 cell counts, while higher CD4 counts have been associated with female sex and smoking." (PMID 23894603, 2013). "Our patients had many of the risk factors for developing TB-IRIS; low CD4 counts, disseminated tuberculosis and relatively short time interval between starting tuberculosis therapy and ART." (PMID 23408935, 2013). "Tuberculosis emerged as the most frequent infection to be associated with HIV infection in patients across the total range of CD4+ followed by oral candidiasis among the spectrum of OIs observed." (PMID 24330921, 2013). "Immunity conferred by antigen-specific CD4+ T cells is critical for controlling infection with Mycobacterium tuberculosis (Mtb), the causative agent of tuberculosis." (PMID 24130562, 2013).
tuberculosis (continued). "Our study also identifies a number of transcriptional signatures in CD4+ T cells that have the potential to be utilized as diagnostic and prognostic tools to combat the tuberculosis epidemic." (PMID 22719887, 2012). "Low CD4 count, history of alcohol intake and history of anti-tuberculosis treatment were strongly associated with HIV-SN (AOR 2.5, 2.8 and 2.9 respectively)." (PMID 23181417, 2012). "The finding that antiretroviral therapy is strongly associated with a reduction in tuberculosis incidence across all CD4 counts is consistent with an earlier meta-analysis that included studies from developed and developing countries." (PMID 22911011, 2012). "Determine TB-LAM is a simple, low-cost, alternative to existing diagnostic assays for tuberculosis screening in HIV-infected patients with very low CD4 cell counts and provides important incremental yield when combined with sputum smear microscopy." (PMID 22015305, 2012). "This seemed to be a valid approach since MHC-II-bound peptides drive CD4-dependent anti-tuberculosis TH1 response, and CD4 T cell deficient human HIV-1 infected patients rapidly succumb due to tuberculosis." (PMID 22574140, 2012). "Antiretroviral therapy is strongly associated with a reduction in the incidence of tuberculosis across all CD4 count strata." (PMID 22911011, 2012). "This review found that antiretroviral therapy is strongly associated with a reduction in tuberculosis incidence in adults with HIV across all CD4 cell counts." (PMID 22911011, 2012). "HIV-positive people are very susceptible to tuberculosis because HIV, the virus that causes AIDS, destroys the immune system cells (including CD4 lymphocytes) that normally combat tuberculosis." (PMID 22911011, 2012). "Since human CD4 T cells are implicated in immunopathology as well as in protective immunity in tuberculosis, identification of correlates of CD4 T cell-mediated immunity, and the design of improved TB vaccines, is proving to be a challenge." (PMID 22880090, 2012). "Antiretroviral therapy causes viral suppression and immune recovery, which reduces tuberculosis incidence by 65% across all CD4 counts." (PMID 22911011, 2012). "HIV-SN was strongly associated with advanced age, low CD4 count, history of alcohol consumption, history of anti-tuberculosis treatment but was modestly associated with sex and height." (PMID 23181417, 2012). "The roleof CD4 T cells in defense against Mtb infection has been inferred from the increasedreactivation of latent Mtb infections in CD4 T cell deficient patients following HIVinfection and severe tuberculosis observed in CD4 T cell-deficient mice." (PMID 21625591, 2011). "After exclusion of patients with tuberculosis co-infection, low CD4 count was the only factor associated with hyperferritinemia." (PMID 21827653, 2011). "In multivariable analysis adjusted for age, sex, body mass index, CD4 count and co-infection with tuberculosis, being on ART was significantly and positively associated with raised total cholesterol, LDL-cholesterol and TC/HDL cholesterol." (PMID 21943115, 2011). "The CD4 deficiency caused by HIV infection is the greatest recognized predisposing factor to tuberculosis and conversely antiretroviral therapy (cART) reduces susceptibility by suppressing viral replication and allowing CD4 recovery." (PMID 21203487, 2010). "Further, patients with CD4 counts <200 cells/μL are at substantially higher risk of tuberculosis compared to those with higher counts." (PMID 20224814, 2009). "We have previously shown that low baseline CD4 count at entry to an ART programme was associated with increased risks of tuberculosis and of mortality during the first year of ART." (PMID 16551345, 2006). "Impaired CD4+ T cell-dependent IFN-γ immunity in LY9-deficient humans underlies tuberculosis." (PMID 40446017, 2025). "CD153, encoded by TNFSF8, is essential for regulating CD4 + T cells in tuberculosis and may influence apoptosis control in septic ARDS." (PMID 39854144, 2025).
tuberculosis (continued). "In addition, changes in the gut microbiota were associated with the number of CD4+ T cells in the peripheral blood of tuberculosis patients." (PMID 40141021, 2025). "BCG-specific CD4 T cells secreting IFN-γ were associated with reduced tuberculosis disease risk in South African infants, which might be important." (PMID 38012890, 2024). "In PLWH, tuberculosis resulted in a higher risk of death when CD4+ counts were < 500 cells/mL." (PMID 37153012, 2023). "In addition, majority of the participants in the Ethiopian study had CD4 counts below 200 cells/mm3, a risk factor for immune reconstitution syndromes including unmasking tuberculosis and other infections affecting liver chemistry." (PMID 36748010, 2023). "People with HIV who had CD4+ counts < 350 cells/mL or viral load ≥ 1000 copies/mL had increased risk of death from tuberculosis compared to virally suppressed patients (adjusted relative risk: 2.10 [95% CI: 1.44–3.04, P < 0.009] and 1.56 [95% CI: 1.22–2.00, P < 0.001])." (PMID 37153012, 2023). "CD4+ T cells are stimulated by specific antigens caused by Tuberculosis (TB)." (PMID 38259491, 2023). "On bivariate logistic analysis, contact history with tuberculosis-infected patients, pneumonia confirmed by chest X-ray examination, and CD4+results were associated factors for M. Tuberculosis; however, none of these factors were associated in the multivariate analysis." (PMID 35913968, 2022). "The risk of tuberculosis incidence among HIV-infected individuals was 2.12 times more likely for those who had less than 200 cells/mm3 at baseline than greater CD4 cell count (HR 2.12; 95%CI 1.31, 3.43; I2 (test) = 90.8% (p < 0.001); publication bias: β (p value) = − 3.16 (0.57))." (PMID 33632342, 2021). "Moreover, alcohol consumption is an established risk factor for tuberculosis in a dose dependent fashion, and exacerbates TB infection by blunting CD4 and CD8 T-lymphocyte cellular responses." (PMID 32778729, 2020). "This might be because HIV positive patients who were on ambulatory or bedridden functional status at baseline might have low CD4 counts that could make them more susceptible to co-infections like tuberculosis." (PMID 32374773, 2020). "Tuberculosis (TB) represents the largest cause of death in human immunodeficiency virus (HIV)-infected individuals in part due to HIV-related CD4+ T cell loss, rendering patients immunocompromised and susceptible to a loss of Mycobacterium tuberculosis control." (PMID 32434838, 2020). "Treatment of latent tuberculosis along with cART for people with HIV is a well evidenced intervention, showing an effect in addition to cART on tuberculosis risk, including among individuals with higher CD4+ cell counts albeit largely demonstrated in high tuberculosis-incidence settings." (PMID 32501837, 2020). "Prioritizing IPT in PLHIV with low CD4+ counts, urban residence and in males may further mitigate the risk of tuberculosis during ART." (PMID 31664933, 2019). "To determine whether T cell differentiation was associated with exhaustion in tuberculosis, we analyzed PD-1 expression in CD4+ memory T cells from active TB and LTBI donors." (PMID 30283456, 2018). "Finally, mRNA expression of exhaustion markers was compared in CD4+ T cells between the cohorts to evaluate a possible causative role of T-cell exhaustion for impaired IL-7 response in tuberculosis." (PMID 28582466, 2017). "The risk of tuberculosis increases up to 30-fold as CD4+ T cells are progressively depleted." (PMID 29029171, 2017). "Higher nadir CD4+ T lymphocyte count (per 100 cells/mm3) was associated with significantly reduced hazard of tuberculosis (HR 0.79, 95 % CI 0.70–0.89), esophageal candidiasis (HR 0.74, 95 % CI 0.62–0.89), cerebral toxoplasmosis (HR 0.62, 95 % CI 0.48–0.81) and PCP (HR 0.58, 95 % CI 0.43–0.79)." (PMID 27001753, 2016).
tuberculosis (continued). "The ability of ART to ameliorate the loss of CD4+ T cells within granulomas may be why this therapy reduced tuberculosis incidence across persons with a wide spectrum of peripheral CD4+ T-cell counts." (PMID 27462092, 2016). "Of note, in Temprano, the trial who assessed in parallel the efficacy of early ART and IPT, IPT also reduced the risk tuberculosis by 66 % overall, 68 % in patients who had less than 500 CD4/mm3 at baseline and 63 % in those who had more than 500 CD4/mm3 at baseline." (PMID 27462361, 2016). "Interestingly, another study found no clear association between the recovery of M. tuberculosis-specific CD4+ T-cells and tuberculosis in association with IRIS." (PMID 25645330, 2015). "Moreover, despite relatively normal numbers of circulating CD4+ T cells HIV-1-infected persons are already at increased risk of tuberculosis in the first year following seroconversion." (PMID 23147374, 2013). "In HIV infection, depletion and functional impairment of CD4+ T cells is a key marker indicating progression to immuno-compromised status, where the host could be rendered more susceptible to malaria, tuberculosis and other opportunistic infections." (PMID 22715396, 2012). "The meta-analysis of these three studies indicated that antiretroviral therapy is strongly associated with a reduction in tuberculosis incidence in adults with CD4 counts above 350 cells/μl (HR 0.43, 95% CI 0.30 to 0.63; p-value for effect <0.001; p-value for heterogeneity = 0.774)." (PMID 22911011, 2012). "The meta-analysis of these four studies found that antiretroviral therapy is strongly associated with a reduction in tuberculosis incidence in adults with baseline CD4 counts from 200 to 350 cells/μl (HR 0.34, 95% CI 0.19 to 0.60; p-value for effect <0.001; p-value for heterogeneity = 0.069)." (PMID 22911011, 2012). "A meta-analysis of these two studies found that antiretroviral therapy is strongly associated with a reduction in tuberculosis incidence in adults with baseline CD4 counts less than 200 cells/μl (HR 0.16, 95% CI 0.07 to 0.36; p-value for effect <0.001; p-value for heterogeneity = 0.609)." (PMID 22911011, 2012). "The higher mortality in HIV associated tuberculosis could be mostly due to other OIs, which occur in the presence of profound immunosuppression as also seen in our study group wherein the median CD4 count was 117/mm3." (PMID 21814542, 2011). "CD4+ T cell count in the majority of the patients in HIV+LTB group was 500/μl, while most patients in group HIV+ATB were CD4+ T cells <200/μl, which possibly indicated the role of CD4+ T cells in controlling TB activation and the high risk of progression from latent infection to active tuberculosis." (PMID 19476627, 2009). "Previous studies have associated baseline CD4+ count, tuberculosis (TB) co-infection, gender, body mass index (BMI), and socio-economic status with immune recovery." (PMID 41472251, 2025). "A CD4+ count below 200 cells/μL has been well documented in numerous studies as a significant risk factor for developing infections such as orofacial manifestations (with oral candidiasis being the most common condition), tuberculosis, PJP, and cryptococcal meningitis." (PMID 40943696, 2025). "In tuberculosis, caused by M. tuberculosis, Th17 cells have been shown to contribute to protective immunity, particularly in the early stages of infection, by playing a role in the induction of chemokines, the recruitment of CD4+ T cells to the site of infection, and the formation of granulomas." (PMID 40569678, 2025). "We characterized Mycobacterium tuberculosis (Mtb)-specific CD4 T-cell phenotype and transcription factor profile associated with the development of TB-IRIS." (PMID 36726536, 2023). "It is commonly recognized that macrophages and CD4+ T cells are the main players in immune responses against Mycobacterium tuberculosis (Mtb), the causative TB agent." (PMID 36674664, 2023).